GDF15 (growth differentiation factor 15)
Diseases named in the same sentence as GDF15 in open-access papers (continued):
Sharing a sentence is not in itself a finding about the gene and the disease.
cancer (continued). "Serum levels of GDF15 are strongly associated with many diseases, and functional roles of GDF15 have been reported in cardiovascular, renal, cancer, and metabolic diseases." (PMID 34335566, 2021). "Our study showed that GDF-15 had a high prognostic value for cancer death in patients with CV risk factors." (PMID 34150865, 2021). "GDF15 is a member of the transforming growth factor-beta superfamily, and its association with cancer can depend on cell state and tumor environment." (PMID 34434660, 2021). "Concerning its role in pathophysiology, GDF15 has been linked to cancer cachexia and side-effects of chemotherapy." (PMID 34831213, 2021). "Conversely, GDF15 antagonists are being developed to treat cachectic states, particularly those associated with cancer." (PMID 34187898, 2021). "Cardiovascular diseases, ineffective erythropoiesis, such chronic diseases as rheumatoid arthritis, end-stage renal failure, and diabetes, and many cancers are associated with a high GDF-15 level." (PMID 34247467, 2021). "Not discrimination (c-statistics) but reclassification (NRI and IDI) was significantly improved with the addition of log GDF-15 to the fully adjusted model for all-cause, cancer, and CV death." (PMID 34150865, 2021). "The potential therapeutic utility of GDF15-GRFAL antagonism has been demonstrated most clearly in the setting of cancer cachexia, where a blocking antibody to GDF15 prevented the cancer cachexia associated with xenograft tumors in mice." (PMID 32310257, 2020). "As seen in these cancers, high expression of GDF15 is associated with poorer survival than in patients with low expression." (PMID 33086658, 2020). "Increased GDF15 in a range of cancer types has been reported to associate with weight loss and is implicated in the pathogenesis of cancer cachexia." (PMID 31853550, 2020). "Further, we determined the role of GDF-15 secreted by exosomes from cancer cells in angiogenesis and its underlying mechanism." (PMID 33193874, 2020). "The cytokine, GDF15, is produced in pathological states which cause cellular stress, including cancer." (PMID 32723474, 2020). "On the other hand, the GDF-15 circulating levels were found higher in cancer patients with body weight loss with respect to those with a stable weight, observations that were also recently confirmed in experimental models." (PMID 33396237, 2020). "In particular, gain- and loss-of-function experiments in mouse models suggest that GDF15 is a mediator of cancer cachexia." (PMID 32757036, 2020). "Higher circulating GDF-15 levels have been proven to be significantly associated with weight loss in cancer patients." (PMID 33312159, 2020). "The cancer-therapeutic drug, cisplatin, induces the release of GDF15 and activates GFRALAP/NTS neurons, as well as causing significant reductions in food intake and body weight in mice." (PMID 32723474, 2020). "The association of raised circulating levels of GDF15 with cancer cachexia make this an obvious area for therapeutic investigation." (PMID 32310257, 2020). "Elevated plasma GDF‐15 is associated with progressing disease severity and poor prognosis in solid tumours of treatment‐naïve cancer patients." (PMID 31463975, 2019). "Stratification by cancer type, test matrix, ethnicity, and cut-off setting also illustrated the robustness of the diagnostic value of GDF-15 in DST." (PMID 30808336, 2019). "In order to identify how GDF15 is implicated in cancer cell migration under solid stress conditions, it was transiently silenced using an shRNA or siRNA-mediated silcening approach." (PMID 30700740, 2019). "On the other hand, at lower cut-off values, GDF-15 levels can predict long-term cardiovascular events, bleeding, cancer, and all-cause mortality, both in patients with chronic heart diseases and in individuals that dwell in community settings." (PMID 31624933, 2019).
cancer (continued). "When considering the relationship between GDF-15 and cancer, this association has already been discussed to a high degree in other reviews." (PMID 31772623, 2019). "This is the first study providing evidence of a functional association between RSU-1 and GDF-15 with regard to cancer cell invasion." (PMID 30621163, 2019). "Accumulated in the cancer cell nucleus, GDF-15 causes a disorder in the expression of genes associated with Smad factors." (PMID 29467963, 2018). "GDF15 was thus considered a novel potential diagnostic and prognostic biomarker for the improved risk assessment of cancer progression." (PMID 29636108, 2018). "GDF15 is predictive not only of cardiovascular disease risk but also of longevity, healthy behaviors, incident cancer, cancer mortality, and biologic age." (PMID 29967567, 2018). "As discussed in the previous section, elevated GDF15 level in serum is associated with many cancers." (PMID 30542297, 2018). "Measurement of serum GDF-15 level has been proposed as an indicator for cancer progression and risk assessment." (PMID 28489602, 2017). "Excessively elevated GDF-15 levels, as seen in chronic inflammatory conditions, cancer and ageing, can cause cachexia." (PMID 27734214, 2017). "A population-based cohort study from Sweden on 876 male volunteers, aged between 35 and 80 years, found that GDF-15 is associated with all-cause (cardiovascular, cancer, etc.)mortality independent from age." (PMID 29180833, 2017). "Whilst its circulating levels are linked to cancer outcome, the role MIC-1/GDF15 plays in cancer development and progression is incompletely understood." (PMID 25695521, 2015). "The association between GDF-15 and future cardiovascular and cancer morbidity and mortality seems very robust, especially as it is most prominent in participants without previous cardiovascular or cancer disease." (PMID 24312445, 2013). "The dysregulation of GDF-15 expression and signaling pathways has been associated with diverse human diseases and cancer progression." (PMID 24236027, 2013). "Univariable and multivariable associations between 1 SD increase of the level of log GDF-15 and 10 years outcome concerning cancer mortality and cancer mortality or morbidity (values are hazard ratios (95 % CI) and p values)." (PMID 24312445, 2013). "Association studies suggest that GDF15 is dramatically induced in liver injury, cancers, cardiovascular diseases, thalassemia and HPV-mediated cervical cancer." (PMID 21625435, 2011). "GDF-15 is a cytokine known to be upregulated in response to cellular stress and tissue injury, with established prognostic and diagnostic value in various conditions, including cardiovascular disease, malignancy, and kidney disease." (PMID 41515626, 2026). "Additionally, several studies have reported promising results for GDF-15 in predicting bleeding risk in other populations, including a small cohort of cancer patients." (PMID 39967200, 2025). "The PROACC-1 trial has already demonstrated that neutralizing GDF15 with ponsegromab leads to weight gain, increased appetite, and improved functional performance, underscoring the role of GDF15 as a central regulator of cancer-associated metabolic dysfunction." (PMID 40868185, 2025). "Recent studies have linked GDF15 to oxidative stress and drug resistance in cancer cells." (PMID 41035818, 2025). "The study also emphasized the significance of LFA-1 in the success of immunotherapy, showing that elevated serum GDF-15 levels in cancer patients were linked to poor outcomes following PD-1 therapy, and that inhibiting GDF-15 improved T cell recruitment and enhanced therapeutic efficacy." (PMID 39911389, 2025).
cancer (continued). "Elevated levels of GDF15 are linked to pathological conditions, including tissue damage and inflammation, as well as to the development of cardiovascular diseases, endocrine diseases (diabetes and obesity) and cancer." (PMID 40128491, 2025). "Elevated levels of GDF15 are linked to pathological conditions, including tissue damage, inflammation, infection, as well as the development of cardiovascular diseases, endocrine diseases (diabetes and obesity), and cancer." (PMID 40565178, 2025). "Serum GDF15 has been linked in recent research to the development of cancer and cardiovascular disease; however, there are still fewer studies examining the connection between serum GDF15 and T2DM in combination with MS, and the clinical application has not yet been promoted." (PMID 41497484, 2025). "Therefore, we aimed to evaluate the ability of GDF-15 to predict bleeding risk in cancer patients initiating systemic anticancer therapies." (PMID 39967200, 2025). "Elevated GDF15 levels are linked to pathological conditions, including tissue damage and inflammation, as well as to the development of cardiovascular diseases, metabolic diseases, and cancer." (PMID 40565178, 2025). "In this study, we demonstrated that elevated GDF-15 levels in cancer patients are significantly and independently associated with an increased risk for major bleeding, even after adjusting for a wide range of clinical, cancer-specific, and laboratory parameters." (PMID 39967200, 2025). "Additionally, GDF-15 plays a critical role in the development of cancer cachexia, a multifactorial syndrome associated with significant morbidity and mortality in cancer patients." (PMID 39766045, 2024). "Growth differentiation factor 15 (GDF‐15) is a cytokine that is implicated in cancer cachexia and may represent both a biomarker of cancer cachexia and a potential therapeutic target." (PMID 38500292, 2024). "Elevated levels of growth differentiation factor 15 (GDF15) are often observed in CC, and the presence of GDF15 in exosomes may be a contributing factor to the appetite suppression and weight loss experienced by cancer patients." (PMID 38802952, 2024). "Recent studies have also demonstrated that neutralizing GDF15 can improve anorexia and weight loss in animal models, alleviate side effects caused by chemotherapy, enhance the quality of life and survival rates in cancer patients." (PMID 39172988, 2024). "Additionally, some studies have shown that high levels of GDF15 are associated with weight loss in animal models and poor survival rates for cancer patients." (PMID 39697630, 2024). "Furthermore, neutralization of Gfral or GDF-15 with antibodies attenuates cancer-associated cachectic phenotypes in animals." (PMID 38824130, 2024). "In cancers, elevated GDF-15 levels are often associated with tumor aggressiveness and poor outcome." (PMID 39283723, 2024). "Another study from Japan also showed that GDF15 could predict cancer mortality among patients with cardiovascular risk factors." (PMID 39625596, 2024). "Furthermore, GDF15 has been shown to play a role in cancer development and associate with prognosis in certain adult cancers." (PMID 38146512, 2023). "While it is debated whether altered GDF15‐levels are a cause or consequence of cancers, their involvement in cancer anorexia has become increasingly recognized." (PMID 36642986, 2023). "Evidence accumulates of a positive association between GDF-15 levels and cancer-induced cachexia." (PMID 36361969, 2022). "GDF15 was implicated in different cardiometabolic disorders and cancer." (PMID 36444166, 2022). "GDF-15 is associated with cardiovascular disease, inflammation, body weight regulation, and cancer." (PMID 34291416, 2022).
cancer (continued). "It is worth mentioning that two small prospective studies, one among diabetics and one among elderly individuals, found positive associations between higher levels of GDF-15 and overall cancer risk; these studies, however, were too small to examine relative risks for individual cancer types." (PMID 34935094, 2022). "Cancer phenotypes were also associated with GDF15 levels, including malignant neoplasm of the respiratory system and intrathoracic organs (OR = 1.6, CI = 1.3–1.8, p-value = 0.0015) and malignant neoplasm of the bronchus and lung (OR = 1.6, CI = 1.3–1.9, p-value = 0.0029)." (PMID 35916366, 2022). "In conclusion, GDF-15 might be a strong predictor for all-cause, cancer, and CV death in patients with CV risk factors." (PMID 34150865, 2021). "Furthermore, we found that the diagnostic and prognostic value of miR-216a and GDF15 in COAD can be extrapolated to other cancer types, including BLCA, CSCA, STAD, and UCEC." (PMID 34948431, 2021). "The present results showed that elevated GDF-15 was associated with increased risks of all-cause, cancer, and CV death in outpatients with CV risk factors, and that incorporating GDF-15 to the predictive model for these outcomes improved its performance significantly." (PMID 34150865, 2021). "Body weight loss resulting from elevated GDF-15 might cause poor prognosis in patients with various types of cancer and CVD." (PMID 34150865, 2021). "Multivariable adjusted Cox regression models were used to assess the association between log-transformed GDF15 (logGDF15) and 12-year mortality outcomes (all-cause, cardiovascular- and cancer-specific outcomes) and interactions with sex, race and poverty status." (PMID 32764826, 2020). "As tumor-promoting inflammation (which has been declared a hallmark of cancer since 2011) critically contributes to spontaneous tumor development in this model, suppression of tumor growth by GDF-15 may be explained by its anti-inflammatory effects." (PMID 32508832, 2020). "Furthermore, elevated serum levels of GDF-15 are linked to cancer-associated anorexia and weight loss in prostate cancer." (PMID 30645608, 2019). "High serum hepcidin and GDF-15 levels were associated with metastases and cancer relapse." (PMID 30646851, 2019). "In T2D patients, increased circulating levels of GDF15 are associated with higher cancer incidence." (PMID 31261735, 2019). "A cancer-associated increase in GDF-15 levels was suggested to have a prognostic potential and therefore might be used as a clinical biomarker." (PMID 30646851, 2019). "Importantly, being that GDF-15 has been associated with actin cytoskeleton reorganization, changes in matrix stiffness and cell morphology, as well as cancer progression, its regulation by RSU-1 seemed of particular importance." (PMID 30621163, 2019). "GDF-15 is also associated with the cachexia associated with cancer." (PMID 29467963, 2018). "In a follow up study performed with the TCGA database (TCGA_CESC_exp_HiSeqV2), women with high GDF15 expression showed a statistically significant higher risk of cancer development and shorter disease-free survival time within 10 years compared to women with low GDF15 expression." (PMID 29636108, 2018). "GDF15 is associated with the development of several age-related diseases including heart failure, coronary artery disease, atrial fibrillation, diabetes mellitus, cancer, and cognitive impairment." (PMID 29967567, 2018). "Interestingly, recent studies have also linked RET to alterations in tumor metabolism, an emerging hallmark of cancer, through a novel ligand complex involving Growth Differentiation Factor 15 (GDF15) and the GDNF Family Receptor α-like (GFRAL)." (PMID 30666215, 2018).
cancer (continued). "The TGFβ signaling pathway has been implicated in development of cachexia, and its superfamily members including TGFβ-1 and Growth Differentiation Factor (GDF-15) have been found to be elevated in plasma of pre-cachectic and cachectic cancer patients experiencing weight loss." (PMID 28177923, 2017). "Because GDF15 modulates ROS generation, we examined whether the GDF15 contribution to cancer stemness is associated with ROS regulatory mechanisms." (PMID 27903972, 2017). "Simply overexpressing miR-873-5p or GDF15 may therefore generate completely different results depending on the cell type-specific machinery and underlying gene expression profiles of the cancer cells in question." (PMID 28806401, 2017). "GDF-15 concentrations are elevated in the situations associated with ineffective erythropoiesis, such as thalassemia syndromes or sickle cell syndromes as well as other conditions like inflammation, acute injury, or cancer." (PMID 27043030, 2016). "Elevated GDF15 levels were correlated with poor patient survival and causative molecular mechanisms including a facilitation of proliferation, migration and invasion of cancer cells were suggested 28,34." (PMID 25823874, 2015). "Many different types of cancers express MIC-1/GDF15 causing elevation in its circulating levels." (PMID 26207898, 2015). "GDF15 expression can be dramatically induced and is implicated as a key secretory cytokine in response to multiple cellular stressors, such as acute injury, inflammation and cancer." (PMID 23799024, 2013). "Several mechanisms might explain the association between the GDF-15 level and cardiovascular and cancer morbidity and mortality." (PMID 24312445, 2013). "In some cancer types, elevated levels of GDF‐15 have been associated with an adverse prognosis." (PMID 24312445, 2013). "GDF15 was originally discovered as a factor in immune regulation and was subsequently considered a host responsive factor linked to tissue injury, cardiovascular events and cancers." (PMID 21625435, 2011). "Therefore, GDF15 was recently reported to be associated with cancer cachexia." (PMID 41016991, 2026). "The anti-GDF15 antibody ponsegromab suppressed serum unbound GDF15 concentrations and was associated with weight gain in patients with advanced cancer in a phase Ib study and led to weight gain and improved cancer cachexia symptoms in patients with cancer in a phase II study." (PMID 40354065, 2025). "Targeting growth differentiation factor 15 may help make cancer cachexia (a syndrome of ongoing weight and muscle loss in patients with cancer) go from an untreatable problem to a manageable condition, while improving both quality of life and treatment outcomes." (PMID 41294666, 2025). "Additionally, GDF-15 as a therapeutic target has significant clinical value in reducing anorexia and weight loss in tumor patients, reversing resistance to chemotherapy drugs, and preventing the spread of cancer." (PMID 38335385, 2024). "The functional significance of such high expression is apparently related to the induction by GDF15 of cachexia, the rapid, extreme reduction in lean body mass, due to loss of appetite and increased catabolism, that represents a primary cause of death from cancer." (PMID 38711789, 2024). "Moreover, GDF-15′s association with cancer cachexia suggests that it may serve as a potential therapeutic target." (PMID 39766045, 2024). "Moreover, it appears that anorexia/cachexia syndrome, which leads to substantial weight loss, associated with cancer development, is likely driven by an increased level of circulating GDF15 that mediates its effect through a central mechanism involving the hypothalamic TGF‐β receptor II." (PMID 36992609, 2023). "GDF15 might be implicated in cancer progression and is also regulated by ISR." (PMID 37525297, 2023).